ZNF727 (zinc finger protein 727)
Description:
May be involved in transcriptional regulation.
Synonyms: ZNF727P
Tractability: PROTAC: ubiquitination databases record sites on it.
Gene: Protein-coding gene on chromosome 7 (64,045,429 to 64,114,556, forward strand). Ensembl gene ENSG00000214652.
Subcellular location: Nucleus
Subcellular location (Human Protein Atlas): Nucleoplasm
Pathways (Reactome):
Gene expression (Transcription): Generic Transcription Pathway
Gene Ontology:
Molecular function: DNA-binding transcription factor activity, RNA polymerase II-specific; RNA polymerase II cis-regulatory region sequence-specific DNA binding; double-stranded DNA binding
Biological process: regulation of DNA-templated transcription; negative regulation of transcription by RNA polymerase II
Cellular component: nucleus; cytoplasm
Genetic constraint (gnomAD): Loss-of-function variants: 9 observed, 8.19 expected, observed/expected ratio (o/e) 1.1, 90% interval 0.66 to 1.78. That is too few expected variants to judge how well the gene tolerates losing a copy. Missense variants: 505 observed, 530.74 expected, observed/expected ratio (o/e) 0.95, 90% interval 0.88 to 1.02. Synonymous variants: 164 observed, 184.7 expected, observed/expected ratio (o/e) 0.89, 90% interval 0.78 to 1.01.
Homologues: Orthologues: mouse Zfp738 (49% identical), mouse Zfp595 (49% identical), mouse Zfp457 (47% identical), rat AABR07009105.1 (43% identical), mouse Zfp953 (30% identical). Paralogues in human: ZNF736 (70% identical), ZNF682 (58% identical), ZNF724 (58% identical), ZNF695 (57% identical), ZNF254 (57% identical), ZNF732 (57% identical), ZNF726 (56% identical), ZNF595 (56% identical), ZNF681 (56% identical), ZNF708 (56% identical), ZNF85 (55% identical), ZNF728 (55% identical), and 164 more.
Diseases named in the same sentence as ZNF727 in open-access papers:
ZNF727 is named in the same sentence as 1 disease in open-access papers, as found by Europe PMC text mining. Sharing a sentence is not in itself a finding about the gene and the disease. The quoted sentences say what the papers report.
breast carcinoma (2 papers, 2022 to 2024). "A number of these, such as CEBPB, ZNF117 and ZNF92, have been previously proposed as breast cancer markers and ZNF273 and ZNF727 have been reported as breast cancer hub genes." (PMID 38561804, 2024).